RNU2-22P (RNA, U2 small nuclear 22, pseudogene)
Gene: Small nuclear RNA gene on chromosome 2 (231,501,990 to 231,502,201, reverse strand). Ensembl gene ENSG00000223198.
Homologues: Orthologues: chimpanzee U2 (100% identical), pig U2 (40% identical), macaque U2 (38% identical), guinea pig U2 (30% identical), rat LOC120099528 (30% identical), pig U2 (29% identical). Paralogues in human: RNU2-41P (38% identical), RNU2-58P (35% identical), RNU2-72P (35% identical), RNU2-12P (34% identical), RNU2-16P (34% identical), RNU2-35P (34% identical), RNU2-55P (34% identical), RNU2-28P (33% identical), RNU2-53P (33% identical), RNU2-60P (33% identical), RNU2-24P (31% identical), RNU2-42P (31% identical), and 64 more.